RNVU1-14 (RNA, variant U1 small nuclear 14)
Synonyms: vU1.14; RNU1-37
Gene: Small nuclear RNA gene on chromosome 1 (145,281,116 to 145,281,279, forward strand). Ensembl gene ENSG00000207501.
Gene Ontology:
Molecular function: pre-mRNA 5'-splice site binding
Biological process: mRNA 5'-splice site recognition
Cellular component: U1 snRNP
Homologues: Paralogues in human: RNU1-1 (91% identical), RNU1-2 (91% identical), RNU1-27P (91% identical), RNU1-28P (91% identical), RNU1-3 (91% identical), RNU1-4 (91% identical), RNVU1-18 (91% identical), RNVU1-29 (91% identical), U1 (91% identical), RNVU1-28 (91% identical), RNVU1-7 (91% identical), RNVU1-31 (90% identical), and 134 more.